CTLA4 (cytotoxic T-lymphocyte associated protein 4)
Diseases named in the same sentence as CTLA4 in open-access papers (continued):
Sharing a sentence is not in itself a finding about the gene and the disease.
tumor (continued). "Pursuing this concept, and mirroring in principle a pharmacological treatment, therapeutic adoptive transfer (ACT) of acute Nr2f6 gene-edited autologous CD3+ T cells into tumor-bearing mice in a combinatorial CTLA-4 or PD-L1 blockade setting was carried out." (PMID 31937317, 2020). "The combined blockade of PD-1 and CTLA-4 enables inactivated tumor-specific T cells to multiply again and perform their effector function." (PMID 31947592, 2020). "We were unable to identify a functional or therapeutic capacity of the endogenous tumor-specific antibody response generated by treatment of B78 tumor bearing mice with RT + IT-IC + anti-CTLA-4." (PMID 32849544, 2020). "It was also recently shown that responders to dual CTLA‐4/PD‐1 checkpoint blockade are enriched for effector memory CD8+ T cells within tumor biopsies." (PMID 32508018, 2020). "Chronic exposure to low IFN-γ levels in H22 hepatoma, MA782/5S mammary adenocarcinoma and B16 melanoma led to tumor development and induction of PD-L1, PD-L2, CTLA-4 and Foxp3 molecules which at least partially mediated tumor immune evasion." (PMID 33005420, 2020). "ICI improve the effects of anti-tumor immunotherapy by blocking the immunosuppressive effect of PD-1/PD-L1, CTLA-4, and other immune checkpoints." (PMID 33680909, 2020). "To test if CTLA-4 levels in tumor-infiltrating cells are higher among activated Treg, we analyzed CTLA-4+ cells for their cell surface CCR8." (PMID 31991588, 2020). "They showed that exhausted CD8+ T cells easily infiltrated the tumour, as demonstrated by the presence of several exhaustion markers, PD-1, 2B4, CTLA-4 and LAG3, at the surface of the isolated cytotoxic T cells." (PMID 32635552, 2020). "LncRNA-TCL6 is positively related to tumor-infiltrating lymphocytes (TILs) infiltration and immune checkpoint molecules, like PD-1, PD-L1, and CTLA-4." (PMID 33148302, 2020). "In mouse colon cancer models, anti-CTLA-4 ICI in combination with Lactobacillus acidophilus lysates improved antitumor immune response through the increase of infiltrated T cells in the tumor microenvironment." (PMID 33375686, 2020). "To further validate the anti-tumor efficacy of the CTLA-4 antibody on different tumor sizes, we measured the Ki-67 IHC expression in the tumor tissue collected from the in vivo study." (PMID 32805718, 2020). "Our data show that Pges silencing slightly potentiated CTLA-4 blockade and promoted tumor rejection in 40% of animals." (PMID 31974367, 2020). "Since Treg has been implicated in pathogenesis and prognosis of multiple cancer types, it is anticipated that anti-CTLA-4 antibodies that effectively and selectively deplete Treg in tumor microenvironment would have a broad impact in cancer immunotherapy." (PMID 31991588, 2020). "Whereas CTLA-4 is constitutively expressed in Tregs; this is only upregulated on activated conventional T cells at lower level compared to Tregs even in the tumor." (PMID 33519807, 2020). "High expression levels of CTLA-4 on Tregs contribute to insufficient Treg depletion, promoting anti‐tumor immunity." (PMID 32785290, 2020). "The combination therapy of CD44-targeted NIR-PIT and CTLA4 blockade showed only similar level of T cell infiltration in tumor beds compared with CTLA4 blockade alone one week after therapy." (PMID 32937841, 2020). "Of mice injected with CTLA-4 blockade, 44% (17/38) experienced relapse after primary tumor resection after at least 150 days of follow-up, whereas 97.4% (38/39) of mice receiving control antibody experienced relapse." (PMID 32630247, 2020). "Inhibiting Ezh2 expression enhances the activity of anti-CTLA-4 treatment and suppresses tumor growth." (PMID 32867025, 2020). "Together, these observations indicate that CTLA-4 induces tumor driver pathways by distinct cellular mechanisms, primarily differing in ERK1/2 and AKT signaling processes." (PMID 32850353, 2020). "CTLA4 indicated a higher density of TILs in ccRCC tumor microenvironment, but an immunosuppressed phenotype." (PMID 33117084, 2020).
tumor (continued). "eTReg also express immune checkpoint molecules (e.g., CTLA-4) to inhibit cytotoxic T-cells and suppress the anti-tumor immune response." (PMID 32575843, 2020). "A preclinical study revealed that intratumoral administration of NDV and systemic CTLA-4 blockade induced inflammatory responses and antitumor effects in both local and distant tumors via the induction of systemic and tumor-specific immune responses." (PMID 33207653, 2020). "To this end, we implanted mice with B16.F10 cells and treated mice with anti-CTLA4 or isotype antibodies on days 3, 7, 10, and 14 and tumor growth kinetics were monitored." (PMID 32641748, 2020). "After that, we further compared CTLA4 expression levels between tumor tissues and normal tissues by using the Oncomine database for an external validation." (PMID 33014010, 2020). "The presence of Bifidobacterium and Bacteroides species in mouse gut microbiota has been correlated with tumour suppression by PD-1 and CTLA-4 blockade, respectively." (PMID 32932843, 2020). "Adding the CTLA-4 to the PD-1/PD-L1 blockade can enhance the immune response against the tumour with an increased likelihood of achieving an objective response, but at the price of increased toxicity." (PMID 33023131, 2020). "The activation of Wnt/β-catenin signal can affect immunotherapy, leading to T cell rejection and tumor resistance to anti-PD-L1/anti-CTLA-4 monoclonal antibodies." (PMID 33344447, 2020). "It is currently believed that the immune checkpoint PD-1 and its ligand PD-L1, as well as CTLA-4, are important factors that inhibit tumor T cell immunity." (PMID 33511267, 2020). "More specifically, within the tumor-infiltrating CD8+ T cells, the presence of the particular population of CD8+ T cells of PD-1+CTLA4+T cells is associated with progression-free survival (PFS)." (PMID 31968651, 2020). "Up-regulated expression of the immune checkpoint molecules, including CTLA-4, PD-1, and PD-L1, has been documented to facilitate tumor immune escape." (PMID 32972405, 2020). "The mAb drug conjugate Ipilimumab binds to CTLA-4, blocking the inhibitory signal, facilitating the killing of tumor cells by cytotoxic T lymphocytes." (PMID 33396766, 2020). "For example, high tumor-infiltrating T lymphocyte content makes PD-1 and CTLA-4 monoclonal antibodies more effective." (PMID 33401247, 2020). "DCs, the essential population for naive T lymphocyte activation, can acquire tolerogenic phenotype due to signals from tumor cells, but also from binding, via CD80 or CD86, to cytotoxic T lymphocyte-associated protein 4 (CTLA-4) expressed by Treg." (PMID 33335860, 2020). "Blockade of LAG-3, TIM-3, TIGIT, and VISTA have shown improved anti-tumor responses in preclinical models when combined with anti-CTLA-4 or anti-PD-1 therapy and are currently being evaluated in clinical trials." (PMID 32111080, 2020). "Comparing all these studies has yielded a common set of genes such as CTLA4, TNFRSF4, TNFRSF18, TIGIT, ICOS, and CCR8 whose expression is higher in tumor‐associated Treg cells as compared to Treg cells from other tissues." (PMID 32272497, 2020). "For example, checkpoint ligand-receptor pairs, such as tumor Treg CD80-Th17 cell CTLA4 and tumor Treg CD274-Th17 cell PDCD1, were identified in our study." (PMID 33584715, 2020). "IDO plays an important role in conferring adaptive tumor resistance to immune lysis since animal model studies have demonstrated that sole blocking of PD-1 or CTLA4 pathway enhances the IDO mediated tumor resistance." (PMID 33014820, 2020). "The researchers showed that not only did their therapy result in CD8 T cells in the tumor, but, when combined with CTLA-4 checkpoint blockade, the abscopal effect was also evidenced." (PMID 33260534, 2020). "The OV-induced increase of T cell numbers within the tumor microenvironment can sensitive tumors to CTLA-4 blockade." (PMID 33172438, 2020).
tumor (continued). "Cox regression models for survival, immunohistochemical, clinical, and pathological findings (tumor-infiltrating CTLA-4+ cells)." (PMID 32785290, 2020). "Recent studies revealed that the tumor immune contexture also essentially contributes to the clinical efficacy of CTLA-4 or PD-1/PD-L1 blockade that induced objective clinical responses and improved survival in patients with various tumor types." (PMID 32194568, 2020). "Combination shIDO-ST treatment with anti-PD-1/CTLA-4 antibodies enhanced tumor growth control, compared to either treatment alone, which was associated with significant intratumoral infiltration by CD8+ and CD4+ T cells." (PMID 33339195, 2020). "Immune checkpoint blockade like CTLA-4 and PD-1/PD-L1 inhibitors has fueled the field of tumor immunology in thyroid cancer, highlighting both the ability of tumor–immune system treatment and the uniqueness of tumor immunotherapy." (PMID 33392186, 2020). "Cytotoxic T lymphocyte-associated antigen 4 (CTLA-4) serves as a negative regulator of immune responses and is essential for modulating anti-tumor immune responses." (PMID 32178688, 2020). "The production of CXCL9 and CXCL10, predominantly by TAMs (CD11b+ Ly6Cint CD11c+ F4/80+), enhances CD8+ T cell infiltration and tumor control in response to combination anti-PD-1 and anti-CTLA-4 in a mouse model of mammary adenocarcinoma." (PMID 32849557, 2020). "These so-called neoantigens can be potent tumour-rejection antigens and appear to be the driving force behind responsiveness to anti-CTLA-4 and anti-PD1/L1-based therapies." (PMID 32019478, 2020). "ICI antibodies (i.e., anti-CTLA-4 or anti-PD-1) are effective in unleashing tumor-induced immunosuppression and activating effector immune cells." (PMID 32050597, 2020). "Under normal circumstances, CTLA‐4 and PD‐1 signals are strictly regulated to allow self‐tolerance; however, tumor cells can use these pathways to evade the immune response and establish a microenvironment conducive to tumor growth." (PMID 34766109, 2020). "Advances in the tumor immunology field has led to the development of inhibitors of immune-checkpoint molecules such as CTLA-4 and programmed cell death 1 (PD-1)." (PMID 32054102, 2020). "Functional characterization of tumor CTLA-4 function proceeded with the study of cell-intrinsic effects of CTLA-4 on B-cells in CLL." (PMID 33384695, 2020). "As expected, the ID-1 antibody inhibited the cell viability and induced cell lysis more efficiently in the IgG1 isotype due to its ability to induce ADCC, not shared by IgG4, which seems to be essential for the full anti-tumor activity of the anti-CTLA-4 mAb." (PMID 32781690, 2020). "Despite adaptive immune cell infiltration in claudin-low tumours, treatment with anti-CTLA-4 and anti-PD-1 antibodies cannot efficiently control tumour growth." (PMID 32680511, 2020). "Some miRNAs with abnormal expression in tumor cells can regulate the surface expression of CTLA-4 in tumor-infiltrating T cells, thereby inhibiting the antitumor immune response mediated by T cells and promoting TIE." (PMID 32561709, 2020). "The expansion of Th1-like CD4 T cells following blockage of CTLA-4 improves anti-tumor responses by enhancing CD8 infiltration, cytotoxic CD8 T cells activity, and T cell memory formations." (PMID 32655545, 2020). "Immune checkpoint inhibitors such as PD-1/PD-L1 and CTLA4 blockade are emerging cancer immunotherapies which block the immunosuppressive mechanisms which help tumor evade immune surveillance." (PMID 32937841, 2020). "Immune checkpoint inhibitors targeting the PD-1/PD-L1 or CTLA-4 pathway to unleash tumor-mediated immunosuppression remarkably improved clinical outcomes for some patients with various types of cancer." (PMID 31980601, 2020). "The clinical success of cancer immunotherapies targeting PD-1 and CTLA-4 has ignited a substantial research effort to improve our understanding of tumor immunity." (PMID 32849557, 2020).
tumor (continued). "Human interferon (IFN)-γ plays a role in tumor immunogenicity widely known as an anti-tumor cytokine but also with a dual role in immune evasion and tumor growth, for example through upregulation of the checkpoint inhibitor PD-L1 and CTLA-4." (PMID 32560316, 2020). "Immune checkpoint immunotherapy employs monoclonal antibodies to target immune checkpoint molecules such as PD‐1 and CTLA‐4 on T‐cells and their ligands PD‐L1 and B7‐H3 on tumor cells, restoring T‐cell anticancer activity." (PMID 33073260, 2020). "Overall, these experiments demonstrate that the addition of anti-CTLA-4 antibody in the tumor fragment cultures can improve the expansion of tumor-reactive TILs." (PMID 32127601, 2020). "A short course of treatment with a Poly(I:C)-based therapeutic combination prior to ICB sensitized several tumor models to anti-CTLA4/anti-PD-L1." (PMID 32133005, 2020). "Blocking the negative regulator of co-stimulation CTLA-4 is a feasible means by which to disrupt the immunosuppressive microenvironment in tumor tissue." (PMID 32983168, 2020). "Our study decodes the heterogenous tumor clusters guided by CTLA-4 expression and activation and suggests the existence of diverse tumorigenic pathways in TNBC in association with CTLA-4 status." (PMID 32850353, 2020). "On the other hand, the expression of inhibitory molecules such as CTLA4, PD-1, and LAG3 on CD8+ T cells are promoted by IL-6 and IL-10, that produced by tumor cells and tumor-associated macrophages, in turn inhibit CD8+ T cells infiltration." (PMID 32208363, 2020). "Similar to CTLA-4, PD-1 is generally upregulated on activated T cells, and negatively regulates T-cell receptor signaling and tumor killing functions by interacting with PD-L1 and PD-L2." (PMID 32260561, 2020). "The [64Cu]NOTA-CD8a tumor-to-heart ratio was increased in XRT + anti-CTLA-4-treated mice on day 8 after initiation of therapy (p = 0.0246)." (PMID 32086762, 2020). "Targeting TGFβ and therapies directed toward PD-1/PD-L1 or CTLA-4 amplifies tumor control by enabling a robust T cell response with improved CD4+ and CD8+ T cell activation and CD8+ T cell cytokine and cell killing capacity." (PMID 32849557, 2020). "CXCR4/CXCL12 axis inhibition has been demonstrated to revert tolerogenic polarization of tumor microenvironment and to restore sensitivity to CTLA-4 and PD-1 ICIs, overall representing a novel and effective way to counteract ICIs resistance." (PMID 33123122, 2020). "The monoclonal antibody ipilimumab binds CTLA-4 and leads to decreased inhibition of the anti-tumor effects of CTLs." (PMID 32944086, 2020). "To confirm distribution of cell-surface CTLA-4 in tumor-infiltrating cells in NSCLC, we analyzed 9 independent fresh NSCLC cancer tissues." (PMID 31991588, 2020). "In this work we evidence that a Foxp3 variant known to affect regulatory T cell functions acts as an hypomorph in a tumor context and enhances the effectiveness of anti‐CTLA4 immunotherapy." (PMID 31729760, 2020). "CD44-targeted NIR-PIT combined with CTLA4 blockade showed greater tumor growth inhibition with longer survival compared with CTLA4 blockade alone in all tumor models." (PMID 32937841, 2020). "The combination of imatinib and CTLA-4 blockade significantly reduced tumour size compared to mice treated with monotherapies." (PMID 33207697, 2020). "In response, checkpoint inhibitors can act as antibodies against immune checkpoint receptors to bind and block the tumor’s inhibitory signaling downstream from CTLA-4 and PD-1, the host immune down-regulation receptors." (PMID 33396766, 2020). "Given the immunosuppressive effects of inhibitory immune checkpoints including PD-1, CTLA-4, and LAG3, and their published role in tumor escape this association seems paradoxical." (PMID 32861198, 2020). "In oncology, immune checkpoint inhibitors (ICI) targeting NCR such as PD1 and CTLA4 have emerged as effective treatments that boost anti-tumour immunity." (PMID 32856125, 2020).
tumor (continued). "Again, the most frequent immune targets in CD4+ T cells from patients with GBM, in descending order, isolated from the tumor microenvironment were A2aR > PD-1 > CTLA-4 > CD39 > TIGIT > FOXP3 > LAG-3 > CD160 > TIM3 > KIR > CD73." (PMID 32721947, 2020). "CTLA-4 blockade has been shown to enhance the activity of endogenous antitumor T cells, thereby inducing tumor regression." (PMID 33294467, 2020). "The immune checkpoints, such as programmed cell death-1 (PD-1)/programmed cell death ligand-1 (PD-L1) and cytotoxic T lymphocyte antigen 4 (CTLA-4), are known to help solid tumors evade host anti-tumor immunity." (PMID 32635549, 2020). "For instance, targeting CTLA-4- and PD-1- expressing lymphocytes has shown to be a potential therapeutic approach towards tumor regression." (PMID 33796822, 2020). "Multiple lines of evidence indicate that immunotherapies, including checkpoint inhibitors such as programmed cell death protein 1 (PD-1) and cytotoxic T-lymphocyte-associated protein 4 (CTLA-4), are efficient strategies to shoot tumor cells." (PMID 33469516, 2020). "Remarkably, we found that blockade of either PD-L1 or CTLA-4 upon ACT of Nr2f6CRISPR/Cas9 knockout CD3+ T cells decelerated tumor growth." (PMID 31937317, 2020). "Consistent with the development of immunologic memory, all ISV + α-CTLA-4 treated complete responders rejected B78 as well as B16 tumor re-engraftment in the contralateral flank (n=22)." (PMID 32690669, 2020). "DNA vaccination targeting CTLA4–PD-L1 triggered the production of specific antibodies and suppressed tumor growth in TAA-induced iCCA rats." (PMID 33255375, 2020). "Immune checkpoint inhibitors (ICIs), including PD-1/PD-L1 and CTLA-4 inhibitors, are monoclonal antibodies that remove tumor cells by activating T lymphocytes and enhancing immune response." (PMID 31959178, 2020). "Entinostat (a histone-deacetylase inhibitor) eradicates 80% tumor and reduces MDSCs combining with CTLA-4 and PD-1 antibodies in different tumor-bearing mouse models, where the administration of each ICI alone is failed to induce anti-tumor response." (PMID 32508809, 2020). "Third, CTLA-4, which is expressed constitutively on Tregs, critically controls Treg functions and modulates anti-tumor immunity." (PMID 32785290, 2020). "Another well-known immune checkpoint is cytotoxic T lymphocyte-associated antigen-4 (CTLA-4), which plays a significant role in tumor tolerance." (PMID 32158356, 2020). "In recent years, immune checkpoint inhibitors that block cytotoxic T-lymphocyte antigen 4 (CTLA-4) and programmed cell death protein 1 (PD-1) have led to significant improvements in prognosis and have brought tumour immunotherapy into a new era28,29." (PMID 31792298, 2019). "Immune recognition of HNSCC in vivo was examined in subcutaneous tumor-bearing C3H mice in the presence of let-7a/b and/or CTLA-4 antibody." (PMID 31881947, 2019). "In mouse models of melanoma, tumor-inherent activation of WNT/β-catenin signaling pathway has been found to restrain T cells from populating the tumor and lead to T-cell exclusion, which in turn results in the primary resistance against PD-L1/CTLA-4 treatment." (PMID 31850199, 2019). "Multivariate analysis revealed CTLA-4 expression as an independent prognostic factor after an adjustment to tumor grade, tumor stage, age, gender, and ECOG performance status." (PMID 31137694, 2019). "The therapeutic efficacy of PD-1 and CTLA-4 checkpoint blockade is thought to be mediated largely through the rescue of exhausted tumour-specific T cells and subsequent restoration of their effector functions." (PMID 30626155, 2019). "Blocking the inhibitory effects of CTLA-4 allows for effective immune responses against tumor cells." (PMID 31253768, 2019).